FRS2 (fibroblast growth factor receptor substrate 2)
Diseases named in the same sentence as FRS2 in open-access papers (continued):
Sharing a sentence is not in itself a finding about the gene and the disease.
ovarian carcinoma (4 papers, 2017 to 2025). A malignant neoplasm originating from the surface ovarian epithelium. "In the in vivo and in vitro experiments with ovarian cancer, FRS2 inhibitors prevented the activation of FRS2 and interrupted the FGFR signaling pathway, thereby inhibiting tumor invasion and growth." (PMID 40225873, 2025). "Our data suggested that tephrosin suppresses the FGFR1/FRS2 signaling pathway in paclitaxel-resistant ovarian cancer cells." (PMID 38137377, 2023). "Previous studies have shown that the overexpression of FRS2 promotes tumorigenesis in ovarian cancer, breast cancer, lung adenocarcinoma, and prostate cancer." (PMID 38137377, 2023). "FRS2 has been identified as one of 50 genes essential for survival in ovarian cancer cell lines." (PMID 38137377, 2023). "Previous studies have reported that FRS2, a downstream factor of the FGFR signaling pathway, is repeatedly amplified in high-grade serous ovarian cancer (HGSOC), which accounts for 70–80% of all ovarian carcinomas." (PMID 38137377, 2023).
sarcoma (4 papers, 2017 to 2025). A usually aggressive malignant neoplasm of the soft tissue or bone. "Our analysis revealed that FRS2 was associated with dendritic cells (Rho = -0.23, P < 0.001) in sarcoma (SARC)." (PMID 40225873, 2025). "The most prevalent mutation types observed were missense and fusion mutations, with FRS2 mutations being most commonly found in sarcoma." (PMID 40225873, 2025). "We utilized the TISIDB and TIMER databases to identify significant immune-related characteristics associated with FRS2 in sarcoma (SARC) (P < 0.05)." (PMID 40225873, 2025). "GEPIA 2 analysis showed significant variation in FRS2 mRNA expression across cancer types, especially in sarcomas (SARC)." (PMID 40225873, 2025). "Tumor specimens from 82 RLPS patients at our sarcoma center were collected, and FRS2 expression was assessed through immunohistochemistry." (PMID 40225873, 2025). "In this study, we utilized publicly available data to investigate the correlation between FRS2 expression and prognosis, aiming to clarify the prognostic significance and related biological functions of FRS2 in sarcoma." (PMID 40225873, 2025). "Specifically, FRS2 mRNA expression was elevated in sarcoma (SARC)." (PMID 40225873, 2025). "This discrepancy may reflect FRS2's predictive value in specific sarcoma subtypes." (PMID 40225873, 2025). "Potentially, this serves as a novel therapeutic target in FRS2 and FGF co-amplified sarcomas." (PMID 28424409, 2017). "High FRS2 expression was correlated with worse DFS and OS in our cohort of 82 RLPS patients, although this association was not significant in the broader TCGA dataset of 259 sarcomas." (PMID 40225873, 2025).
glioma (3 papers, 2014 to 2019). A benign or malignant brain and spinal cord tumor that arises from glial cells (astrocytes, oligodendrocytes, ependymal cells). "The reduction of FGFR activation by MPI knockdown also resulted in decreased downstream signaling through FRS2 and either AKT or MAPK in the U-251 and SKMG-3 glioma cell lines, respectively." (PMID 25314669, 2014).
melanoma (3 papers, 2011 to 2022). A malignant, usually aggressive tumor composed of atypical, neoplastic melanocytes. "Additionally, our results emphasize the potential of the EPHA3 and FRS2 gene products, involved in angiogenesis and migration, as possible therapeutic targets in melanoma." (PMID 21494657, 2011). "EPHA3 and FRS2 are SCNA-affected genes whose products participate in angiogenesis and migration and have the potential to be therapeutic targets for melanoma." (PMID 35157610, 2022). "In our data FRS2 was both focally amplified and over expressed in two melanoma samples (LAU-T149D and LAU-Me275) and amplified (CN = 4) in two additional melanomas (LAU-T618A and LAU-Me235)." (PMID 21494657, 2011). "FRS2 has been suggested as a therapeutic target in cancer and because of its downstream activities to FGFR and other receptors, it might offer new insights in melanoma treatment." (PMID 21494657, 2011).
neuroblastoma (3 papers, 2022 to 2025). Neuroblastoma (NB) is the most common solid, extracranial childhood tumor. "For example, the co-amplification and resulting overexpression of MDM2/CDK4/FRS2 in neuroblastoma patient M787AAA is clinically relevant, and the fusions originating from this amplification are more likely to be passenger events." (PMID 37400763, 2023).
acute myocardial infarction (2 papers, 2022 to 2024). Necrosis of the myocardium, as a result of interruption of the blood supply to the area. "In a rabbit model of myocardial infarction and in H9c2 rat cardiomyoblasts, miR-145 was shown to have a cardioprotective effect through the induction of cardiomyocyte autophagy by targeting fibroblast growth factor receptor substrate 2 (FRS2)." (PMID 35326433, 2022).
glioblastoma (2 papers, 2020 to 2023). The most malignant astrocytic tumor (WHO grade IV). "Consistent with previous studies on head and neck malignancies and glioblastoma, attenuation of FGFR3-TACC3 activation decreased phosphorylation of FRS2, AKT and ERK." (PMID 31987043, 2020).
leiomyosarcoma (2 papers, 2017 to 2020). An uncommon, aggressive malignant smooth muscle neoplasm, usually occurring in post-menopausal women. "However, mRNA did not appear to translate efficiently in protein since the level of FRS2 protein in WDLPS/DDLPS cells was not higher than in the IB136 leiomyosarcoma (LMS) cells." (PMID 33092134, 2020).
malignant glioma (2 papers, 2014 to 2024). A grade III or grade IV glioma arising from the central nervous system. "Loss of MPI activity reduced phosphorylation of FGFR family receptors in U-251 and SKMG-3 malignant glioma cell lines and also resulted in significant decreases in FRS2, Akt, and MAPK signaling." (PMID 25314669, 2014).
serous ovarian cancer (2 papers, 2019 to 2022). "Activation of FGFR signaling pathway as a result of FRS2 adapter amplification was recently identified in high-grade serous ovarian cancer and liposarcoma." (PMID 30755618, 2019).
anemia (1 paper, 2015). A reduction in the number of red blood cells, the amount of hemoglobin, and/or the volume of packed red blood cells. "The highest FRS2α expression levels were associated with a shorter PFS after adjustment for study treatment, baseline anemia or performance status." (PMID 25900027, 2015). "Multivariate Cox proportional hazards regression models were constructed for FGFR1 and FRS2α individually, adjusting for baseline Eastern Cooperative Oncology Group performance status, treatment arm and anemia status." (PMID 25900027, 2015). "Multivariate Cox proportional hazards regression models were constructed for FGFR1 and FRS2α individually, adjusting for baseline ECOG performance status, treatment arm and baseline anemia." (PMID 25900027, 2015).
bladder tumors (1 paper, 2025). "For instance, high FRS2 expression in bladder tumors has been shown to impair endothelial cell recruitment and tube formation, contributing to adverse outcomes." (PMID 40225873, 2025).
cyst (1 paper, 2016). A sac-like closed membranous structure that may be empty or contain fluid or amorphous material. "We found that kidneys lacking Frs2α in nephron progenitors develop rapid cyst growth after birth." (PMID 27853247, 2016).
diabetes (1 paper, 2022). "To assess this possibility, we first evaluated the effects of JQJTT on FGFR1 and its downstream substrate FRS2 in the liver of mice with STZ-induced diabetes." (PMID 35935824, 2022). "In mice with STZ-induced diabetes, fasting blood glucose levels were significantly decreased after 4 weeks of treatment with JQ-R, whereas the phosphorylation level of FGFR1 and that of its intracellular substrate FRS2, as well as the protein levels of GLUT-1, were markedly increased." (PMID 35935824, 2022).
large cell carcinoma (1 paper, 2011). A malignant epithelial neoplasm composed of large, atypical cells. "Furthermore, an elevated level of phosphorylation of the FGFR1 substrate FRS2 was observed in NCI-H1581 large cell carcinoma cells carrying focal amplification of FGFR1, but not in cells harboring relatively broader levels of FGFR1 amplification." (PMID 21666749, 2011).
lipoma (1 paper, 2021). A benign, usually painless, well-circumscribed lipomatous tumor composed of adipose tissue. "The sensitivity and specificity of FRS2 IHC for distinguishing ALT/WDL from normal fat tissue and other benign adipose tumors (lipoma, spindle cell lipoma) were 91.2 and 80.0%, and those of 2+ FRS2 were 54.9 and 100.0%, respectively." (PMID 34696768, 2021).
lymph node metastasis (1 paper, 2017). "In addition to poor tumor differentiation, lymph node metastasis, resection margin, and advanced TNM stage, univariate survival analyses revealed that the expression of GAB2, CRKL, FRS2 and the co-expression of GAB2/CRKL/FRS2 were also indicators for poor clinical outcome." (PMID 28558797, 2017).
Obesity (1 paper, 2021). Accumulation of substantial excess body fat. "In the present study, the DEPs included Frs2 and Shc3, which represent novel candidate pharmaceutical targets for obesity based on their close links to pathways involved in obesity." (PMID 34840970, 2021).
pancreatic ductal adenocarcinoma (1 paper, 2017). An infiltrating adenocarcinoma that arises from the epithelial cells of the pancreas. "The purpose of the present study was to explore the expression and prognostic value of three adaptor proteins: GRB2-associated binding protein 2 (GAB2), CRK-like protein (CRKL) and fibroblast growth factor receptor substrate 2 (FRS2) in pancreatic ductal adenocarcinoma (PDAC)." (PMID 28558797, 2017).
pleomorphic liposarcoma (1 paper, 2021). Pleomorphic liposarcoma (PLS), the rarest subtype of liposarcoma (LS), is an aggressive, fast growing tumor located usually in the deep soft tissues of the lower and upper extremities. "Moreover, among the 15 cases with 1+ FRS2 expression, 2 tumors also harbored a polysomic pattern (1 pleomorphic liposarcoma and 1 undifferentiated pleomorphic sarcoma)." (PMID 34696768, 2021). "It should be mentioned that the FISH analysis of the pleomorphic liposarcoma with 2+ positivity showed polysomic for CEP12, which may lead to FRS2-immunopositivity in this case." (PMID 34696768, 2021).
prostate tumors (1 paper, 2019). "We have demonstrated the prognostic features of FGFR1, FRS2, S6K1, LDHB, MYPT1, and P-LDHA in prostate tumors using tissue microarrays (TMAs) which consist of 241 patient samples from Massachusetts General Hospital (MGH)." (PMID 31316912, 2019).
small cell lung carcinoma (1 paper, 2025). Small cell lung cancer (SCLC) is a highly aggressive malignant neoplasm, accounting for 10-15% of lung cancer cases, characterized byrapid growth, and early metastasis. "In small cell lung cancer (SCLC), FGFR inhibitors demonstrated delayed progression in both in vivo and in vitro experiments by inhibiting downstream MAPK and PI3K-Akt signaling pathways through the inhibition of FRS2 phosphorylation." (PMID 40225873, 2025).
spindle cell tumors (1 paper, 2021). "In differentiating DDL from other spindle cell tumors, the sensitivity and specificity of FRS2 were 96.7 and 65.5%, respectively." (PMID 34696768, 2021).
thyroid cancer (1 paper, 2011). "Conversely, in thyroid cancers FRS3 expression was unchanged but FRS2 expression was increased suggesting potential tissue specific FRS2 and FRS3 changes in tumours." (PMID 22078327, 2011).
tumor (45 papers, 2010 to 2026). "Exploratory biomarker analysis showed FGFR3, FGFR1, FGF-ligand and fibroblast growth factor receptor substrate 2 (FRS2) expression in the patient’s tumour, together with the presence of a germ-line mutation in the FGFR3 extracellular binding domain." (PMID 26497743, 2015). "The combination of dovitinib + NVP-BEZ235 causes tumor stasis and strong down-regulation of the FRS2/Erk and PI3K/Akt/mTOR signaling pathways." (PMID 23343422, 2013). "Notably, we find recurrent ADGRG6 enhancer mutations and FRS2 duplications which are associated with higher protein expression in the tumor and poor prognosis." (PMID 30755618, 2019). "Experimental results indicate that reducing FRS2 expression in bone metastatic tumor cells can reduce the proliferation, migration, and angiogenesis of endothelial cells." (PMID 40225873, 2025). "Along with performing enrichment analysis of FRS2, we explored the relationship between FRS2 expression and the tumor-immune microenvironment (TIME)." (PMID 40225873, 2025). "It then compared second-generation covalent pan-FGFR inhibitors (FIIN1/FIIN2) with a downstream FRS2α inhibitor (FRS2αi) in both tumor cells and CAFs." (PMID 41514658, 2025). "The TISIDB database was used to analyze the relationship between FRS2 expression and the abundance of tumor-infiltrating lymphocytes (TILs), two types of immunomodulators, and chemokines." (PMID 40225873, 2025). "FRS2 was found to inhibit MHC-mediated tumor immune antigen presentation (red frame), with HLA-A being the most significantly affected MHC molecule (R = -0.423, P < 0.001)." (PMID 40225873, 2025). "Collectively, upregulation ofmiR-590-5p can mitigate TC tumor growth in vivovia reduced FRS2 expression." (PMID 40834280, 2025). "We observed a significant increase in FRS2 expression across most cancer types in paired tumor samples compared to their corresponding normal samples." (PMID 40225873, 2025). "Fibroblast growth factor receptor substrate 2 (FRS2) exhibits high positivity rates in primary RPLS tumor specimens, demonstrating significant correlation with recurrence dynamics and survival outcomes." (PMID 40421219, 2025). "FRS2 alterations were identified in 329 of 10,967 tumor samples, representing approximately 3% of all cases." (PMID 40707918, 2025). "We then investigated how FRS2 expression correlates with the tumor immune microenvironment and immune cell infiltration in SARC." (PMID 40225873, 2025). "In cases with PLEKHA5 and FRS2 rearrangements that were multi-sampled, the respective fusions were present in all investigated tumour materials (core needle biopsy, resection specimen, recurrence and/or metastasis), except for Case 12 (FRS2::ADAM32)." (PMID 39322633, 2024). "Our aim was to achieve repression of FGFR-driven tumor growth and progression through interfering with FRS2 function as an alternative targeting strategy." (PMID 36495366, 2023). "Whereas Met inhibition alone exerted a limited effect on FRS2 phosphorylation in tumourspheres, Crizotinib was sufficient to reduce FRS2 phosphorylation in tumours to a level similar to FGFR inhibitor." (PMID 33772015, 2021). "Firstly, we detected the expression of FRS2 in tumor tissues and normal tissues of patients with GCTB." (PMID 32154662, 2020). "bFGF accumulates in MB tumor tissue in a pattern reminiscent of tumor-infiltrating cells, and it is a potent promoter of cell dissemination by signaling via an FRS2-dependent cascade." (PMID 31835472, 2019). "Among the altered genes observed in the tumor sample, an amplification of FRS2, the gene coding for fibroblast growth factor receptor substrate 2, was revealed." (PMID 28955656, 2017). "Staining patterns of anti-GAB2 and anti-CRKL antibodies were both cytoplasmic and nuclear in the tumor regions, while that of the anti-FRS2 antibody was cytoplasmic and membranous in the tumor regions." (PMID 28558797, 2017).
tumor (continued). "This conclusion was borne out by increased blockage of FRS2 activation and increased anti-tumor effects when an agent that blocks the ER was combined with a pan-FGFR inhibitor." (PMID 28445992, 2017). "We co-stained tumor sections for phospho-FRS2 and murine CD31 to determine if FGF2 signaling was affected by [NSIS6S]-[NSIS]5 treatment in specific cell types in tumors." (PMID 27490176, 2016). "Analysis of The Cancer Genome Atlas (TCGA) data set shows that in UC, 10 out of 11 MDM2-amplified tumours are also FRS2-amplified and NanoString analysis confirmed high FRS2 expression in our patient’s tumour sample." (PMID 26497743, 2015). "Work in other tumour models have conversely shown differences in FRS2 and FRS3 between benign and cancers with specific down-regulation of FRS3 or FR2 over-expression." (PMID 22078327, 2011). "Moreover, overexpression of key FGFR-associated signaling nodes, such as FGFR substrate 2 (FRS2), amplifies mitogen-activated protein kinase-extracellular signal-regulated kinase signaling, thereby promoting tumor survival." (PMID 41584352, 2026). "Additionally, we explored the impact of FRS2 on tumor immunity, offering new perspectives for immunotherapy in RLPS." (PMID 40225873, 2025). "FRS2 may affect the tumor immune microenvironment, inhibiting immune cell infiltration and promoting immune evasion." (PMID 40225873, 2025). "It binds to the third immunoglobulin region of the FGFR2b receptor, blocks the activation of FGFR2b and downstream FRS2 (fibroblast growth factor receptor substrate 2) phosphorylation, as well as enhances the antibody-dependent cellular toxicity against tumor cells that express FGFR2b." (PMID 38255923, 2024). "In the 6 FRS2-immunonegative cases, effect of storage time and tumor necrosis or hemorrhage of some samples (5/6) may be related to false negative results." (PMID 34696768, 2021). "Furthermore, patients co-expressing GAB/CRKL/FRS2 in the tumor had a significantly worse outcome than those with single marker expression." (PMID 28558797, 2017). "This patient case highlights that, in addition to patients harbouring FGFR3 hotspot mutations or fusions in their tumour, there is potential for additional UC patients with high expression of FGFR pathway components such as FGFR, ligand and FRS2 to gain benefit from FGFR inhibitor therapy." (PMID 26497743, 2015). "FRS2 is thought to induce tumor progression through stimulation of angiogenesis." (PMID 24575749, 2014). "Overexpression of FRS2 reversedthe effects of miR-590-5p overexpression, limitingmitochondrial respiration and proliferation, and promoting apoptosis.In vivo, overexpression of miR-590-5psuppressed xenograft tumor growth in mice by reducing the transcription ofFRS2." (PMID 40834280, 2025). "FRS2 may also be involved in alternative signaling pathways to promote tumor growth." (PMID 36495366, 2023). "Besides, siRNA targeting FRS2 confirmed that interruption of its expression in GCTBSC could alleviate the tumor activities." (PMID 32154662, 2020). "Furthermore, mRNA of FRS2 could be targeted and repressed by the two microRNAs, so as to compromise the tumor activities." (PMID 32154662, 2020). "Finally, we co‐transfected plasmids expressing FRS2 with the two kinds of mimics into GCTBSC to verify that the plasmids can exacerbate the tumor activities, while the addition of the two mimics could recover the influence of the plasmids." (PMID 32154662, 2020). "FRS2 expression varies across immune-related molecular and immune subtypes in SARC, potentially impacting anti-tumor immunotherapy and survival through immune infiltration." (PMID 40225873, 2025). "Fibroblast growth factor receptor substrate 2 (FRS2) is a key adaptor protein in the FGFR signaling cascade, mediating downstream RAS-MAPK and PI3K-AKT activation, and promoting tumor proliferation and survival." (PMID 40707918, 2025).